INS (insulin)
Diseases named in the same sentence as INS in open-access papers (continued):
Sharing a sentence is not in itself a finding about the gene and the disease.
diabetes (continued). "This is not surprising, because more than 800 million people around the world have diabetes, a chronic metabolic disorder characterized by elevated blood glucose levels resulting from insufficient insulin production or ineffective insulin utilization." (PMID 40863005, 2025). "Diabetes mellitus (DM) is a metabolic condition marked by abnormally high blood glucose levels, which arise due to either inadequate insulin production or the body’s reduced ability to effectively utilize insulin." (PMID 40599550, 2025). "In this review, we highlighted the significance of mitochondrial functionality in diabetes, concentrating on elements such as mitochondrial energy metabolism, oxidative stress, and their interplay with insulin sensitivity." (PMID 40862129, 2025). "We also evaluated the effects of canagliflozin on kidney, cardiovascular and safety outcomes, including diabetic ketoacidosis, by baseline insulin use." (PMID 40036884, 2025). "In diabetes, these mechanisms are critical for maintaining β-cell integrity and regulating programmed cell death in insulin-resistant tissues." (PMID 41155632, 2025). "In adult mice, loss or dysfunction of MafA impairs the ability of β cells to maintain their mature phenotype, resulting in a reduced β cell/α cell ratio, impaired insulin production, and β cell failure in diabetes." (PMID 40906536, 2025). "Messages included: ‘let me have control of my insulin’ and ‘include me in decisions about my diabetes and insulin treatment’." (PMID 41358572, 2025). "Diabetes mellitus is a group of complex metabolic disorders characterized by chronic hyperglycemia, which is characterized by glucose imbalance, insulin resistance, and dysfunction of pancreatic β-cells." (PMID 40474972, 2025). "This group of substances includes cortisol—a stress biomarker, insulin—for diabetes care, testosterone and estrogen—which indicate reproductive and endocrine function, and thyroid hormones (T3, T4, TSH)." (PMID 40507811, 2025). "Faecalibacterium prausnitzii, a species from this genus, has been identified as a potential target for diabetes prevention or treatment strategies, such as prebiotics or probiotics, due to its role in producing butyrate, which enhances insulin homeostasis." (PMID 40033386, 2025). "The pathophysiology of diabetes is largely influenced by glucose metabolism, which is modulated by insulin." (PMID 40508014, 2025). "The regulation of blood glucose levels and insulin sensitivity is fundamental to metabolic health, particularly for type 2 diabetes mellitus, MASLD, and MASH." (PMID 41009545, 2025). "Diabetes mellitus encompasses a group of metabolic disorders that arise when the body cannot properly regulate blood glucose levels, due to either inadequate insulin secretion, or insulin resistance, or both." (PMID 40056450, 2025). "Diabetes mellitus is a metabolic syndrome characterized by hyperglycemia resulting from insufficient insulin secretion or action." (PMID 39657836, 2025). "Smokers with diabetes frequently require higher insulin dosages to maintain blood sugar levels that are near the target." (PMID 40416705, 2025). "SCT that aim to improve insulin independence at the source represent an innovative approach in the treatment strategies for diabetes." (PMID 40959421, 2025). "Factors such as insulin therapy, the duration of diabetes, and overall metabolic control can all play a role." (PMID 41470880, 2025). "Third, the propensity-score matched cohort only had 735 patients per group, which meant that the sample size was too small to allow for meaningful subgroup comparisons such as insulin-treated versus orally treated diabetes." (PMID 41212864, 2025). "Despite the patient’s treatment with insulin and vildagliptin, her diabetes appeared to be becoming out of control." (PMID 40558674, 2025).
diabetes (continued). "As previously reported, administration of STZ induced diabetes with a decrease in the serum concentration of insulin and increases in the serum concentrations of glucose and fructosamine in relation to the healthy control rats." (PMID 39861446, 2025). "Patients were stratified by fasting blood glucose (FBG) levels, use of metformin and insulin, and diabetes duration." (PMID 40764810, 2025). "This led to better glycemic control, increased insulin sensitivity, reduced oxidative stress, and improved kidney structure with less inflammation and fibrosis, suggesting its potential in mitigating diabetes-related renal complications." (PMID 41178959, 2025). "Metformin and insulin are commonly used to manage diabetes, although usually high doses of insulin are required due to the degree of insulin resistance." (PMID 41476924, 2025). "Diabetes patients had more understanding of diabetes, whereas less knowledge of the complications of insulin." (PMID 41306599, 2025). "Some research have focused on the effects of AP on resistance of insulin, which increases the possibility of diabetes." (PMID 40308406, 2025). "Levothyroxine replacement therapy was initiated for hypothyroidism, whereas diabetes ketoacidosis during hospitalization required intensive insulin therapy combined with fluid resuscitation." (PMID 40388765, 2025). "A similar cross‐sectional study was conducted at Chitwan Medical College Teaching Hospital, Bharatpur, Nepal, to assess the insulin injection practice of patients with diabetes." (PMID 41306599, 2025). "Diabetes self-care behaviors refer to the daily health-related activities, such as management of blood glucose, insulin administration, physical activity, dietary habits, and so on." (PMID 41181380, 2025). "Diabetes mellitus (DM) is a group of metabolic disorders characterized by persistent hyperglycemia due to defects in insulin secretion or impaired insulin action." (PMID 40255406, 2025). "PDX1 and MAFA transcription factors have been precisely delivered to pancreatic α-cells using AAV8 vectors, reprogramming them into cells that produce insulin and restoring normal blood glucose levels in rats with diabetes." (PMID 41226304, 2025). "Diabetes is a metabolic disorder with multiple etiologies, characterized by chronic hyperglycemia stemming from defects in insulin secretion, insulin action, or both, which leads to disturbances in carbohydrate, fat, and protein metabolism." (PMID 40134912, 2025). "In summary, while combining a GLP-1RA with insulin represents a valid pathway to achieving diabetes remission, its efficacy depends on selecting an appropriate GLP-1RA formulation and treatment duration." (PMID 41427055, 2025). "Of the 75 participants with obesity, 34 were hypertensive (~45%), 42 were insulin resistant or had diabetes (56%), 38 were dyslipidemic with disrupted lipid profile (~51%), and 46 had steatotic liver (~61%)." (PMID 40548377, 2025). "This has been observed in Iran, where sanctions led to persistent shortages of insulin and diabetes management supplies." (PMID 41343509, 2025). "Diabetes mellitus is a group of metabolic disorders marked by chronic hyperglycemia, which results from abnormalities in insulin secretion, insulin action, or both." (PMID 39942757, 2025). "Curcumin’s ability to improve insulin signaling has been documented in studies of diabetes, obesity, and IR models, where it often enhances the IRS-Akt pathway." (PMID 39103711, 2025). "Novel diabetes drugs have recently been developed, and the mechanisms of these drugs are enhancing insulin secretion responding to postprandial hyperglycemia through GLP-1 signaling and inhibition of glucose absorption via SGLT2." (PMID 39899133, 2025). "Further, this study assessed children during the first year following diabetes diagnosis (selected as a time of systematic CD screening in our practice), when some endogenous insulin and glucagon production remains and can mitigate hypoglycemia." (PMID 40990290, 2025).
diabetes (continued). "This study aimed to assess the impact of insulin pump therapy on glycemic control and acute diabetes complications among patients with type 1 diabetes mellitus at King Fahad Armed Forces Hospital (KFAFH), Jeddah." (PMID 41146752, 2025). "It is widely recognized that all forms of diabetes share a commonality in dysfunctional pancreatic β cells negatively affecting insulin secretion." (PMID 40002796, 2025). "Diabetes mellitus (DM) is a group of metabolic disorders characterized by hyperglycemia, resulting from definitive insulin function and/or reduced insulin production." (PMID 39907816, 2025). "This sequence of pathological changes culminates in impaired insulin secretion and the eventual onset of diabetes mellitus (DM)." (PMID 40075815, 2025). "Diabetes is a chronic inflammatory disease characterized by consistently high blood glucose levels, which result from defective insulin secretion or impaired insulin action." (PMID 40723793, 2025). "All of these observations make sense since adherence to daily insulin therapy is well documented to improve glycaemia for people with diabetes treated with insulin, either as basal or bolus doses." (PMID 41039947, 2025). "To further validate the effects of the SARS‐CoV‐2 spike protein on insulin sensitivity and the metabolic benefits of metformin, we employed a well‐established mouse model of diabetes (db/db mice)." (PMID 41190280, 2025). "This leads to beta-cell destruction and a consequent reduction in insulin secretion, resulting in elevated blood glucose levels, exacerbating pre-existing diabetes, or triggering de novo diabetes." (PMID 40075801, 2025). "Those who lived with diabetes and treated it with insulin for a long time had scores that were somewhat lower for HRQoL." (PMID 40837917, 2025). "Resveratrol has shown to improve FBG, insulin sensitivity, HbA1c, and homeostasis model assessment of insulin resistance values in participants with type 2 diabetes mellitus and obesity." (PMID 40035065, 2025). "Capturing the experience of people with diabetes is key in the context of system‐based approaches to increasing resilience in insulin safety." (PMID 41358572, 2025). "STZ induces diabetes in mice by damaging the pancreatic beta cells of the mouse and thereby reducing insulin production." (PMID 40572277, 2025). "The pancreas, particularly the insulin-producing islets of Langerhans, is a key target for mRNA therapies aimed at diabetes." (PMID 41438702, 2025). "Lipid metabolism and intestinal inflammation in cats is an increasingly common problem, and too much body fat produces insulin resistance, which can lead to serious complications such as diabetes and hepatic lipidosis." (PMID 40508996, 2025). "Diabetes mellitus is a chronic metabolic disorder of hyperglycemia caused by either an absolute deficiency of insulin secretion (Type 1 diabetes, T1DM) or an impaired insulin sensitivity (Type 2 diabetes, T2DM)." (PMID 41301440, 2025). "Evidence indicates that dietary-derived microbial metabolites positively modulate insulin secretion, sensitivity, and diabetes incidence." (PMID 40896191, 2025). "Approximately 5–10% of all people with diabetes have T1D, an autoimmune disease in which the insulin-producing beta cells in the pancreas are destroyed." (PMID 40316962, 2025). "Diabetes mellitus (DM), a chronic metabolic disorder, is distinguished by hyperglycemia arising from impaired insulin secretion, reduced insulin efficacy, or a combination of both factors." (PMID 41195211, 2025). "It is shown to result in the patient gaining increased independence, which is positive, and a sense of security in managing their blood sugar with reminders to those around them, so that patients with diabetes take actions such as eating or taking insulin." (PMID 40281899, 2025). "Insulin dose adjustment—both basal and bolus—is therefore highly individualized and frequently modified by the diabetes care team and progressively by families and patients themselves." (PMID 41323155, 2025).
diabetes (continued). "Glucose intolerance can, under some conditions, progress to type 2 diabetes mellitus (T2D), where insulin is insufficiently utilized." (PMID 41007744, 2025). "In this study, we investigated the relationship between diabetes-specific eating disorder risk, as measured by the DEPS-R, and insulin therapy methods." (PMID 41010976, 2025). "The survey of available literature highlights the effects of K. pinnata on indices of diabetes mellitus, including enhancing insulin sensitivity, mitigating oxidative stress and inflammation, lowering blood glucose levels, and the potential adverse effects." (PMID 41155632, 2025). "Building upon these diagnostic insights, our treatment-based analysis further revealed strong immunological evidence suggestive of diabetes misclassification, particularly among insulin-treated patients initially labeled as T2DM." (PMID 41008668, 2025). "Its positive influence on glycolysis, glycemic control, and insulin responses positions D-tagatose as a promising alternative for managing diabetes mellitus and obesity." (PMID 39861422, 2025). "More than 200 million people worldwide currently use exogenous insulin once or more times a day to treat diabetes." (PMID 40465596, 2025). "C-peptide measurements can provide estimates of insulin secretory capacity, aiding in clinical decision-making and differentiation between diabetes types." (PMID 40093566, 2025). "Despite the accelerated diabetes reversal and improved euglycemic rates in females, male mice exhibited a higher percentage of insulin‐positive cells as well as a higher porcine insulin graft content than females." (PMID 40243327, 2025). "In diabetes, particularly T2DM, reduced NO bioavailability is linked to impaired insulin signaling pathways." (PMID 41394126, 2025). "AI-based systems recommended daily insulin basal rates, prandial insulin doses, or insulin bolus doses for patients with diabetes and the next medication dosage for patients receiving anticoagulation therapy." (PMID 40198108, 2025). "This pattern likely reflects multiple factors including limited access to continuous glucose monitoring, insulin pump therapy, and diabetes education resources." (PMID 41155857, 2025). "These drugs exhibit therapeutic benefits in diabetes by modulating macrophage activity and promoting an anti-inflammatory environment, as well as by directly improving insulin sensitivity in critical tissues." (PMID 41472730, 2025). "Type 1 diabetes mellitus (T1D) is an autoimmune disease that targets pancreatic β-cells, resulting in impaired endogenous insulin secretion." (PMID 41153727, 2025). "Metformin is the most commonly used treatment to improve insulin sensitivity in insulin-resistant conditions such as diabetes, prediabetes, polycystic ovary syndrome, and obesity." (PMID 40781685, 2025). "It is not absolutely necessary to know the type or pathogenetic origin of an individual's diabetes to manage their insulin therapy." (PMID 40035222, 2025). "Several experimental studies have revealed that normal basal HGP can be maintained prior to the onset of diabetes, as the elevated insulin level is sufficient to offset hepatic insulin resistance." (PMID 40568093, 2025). "Type 2 diabetes mellitus (T2DM) is a chronic metabolic disorder characterized by hyperglycemia resulting from impaired insulin secretion, insulin resistance, or a combination of both." (PMID 39912024, 2025). "Remarkably all six mice treated with immune sera remained diabetes free (6/6) with intact pancreases and islets expressing insulin and glucagon." (PMID 40760251, 2025). "The clinical characteristics of the patients revealed that 58.91% had diabetes for less than 5 years, with 46.04% on insulin monotherapy and 64.85% having suboptimal glycemic control." (PMID 41218056, 2025). "Participants mostly reported that diabetes treatment includes a combination of insulin, oral drugs, and exercise." (PMID 41487779, 2025).
diabetes (continued). "An animal model study in mice indicated that hepatic insulin resistance can lead to glucose intolerance, with impaired insulin signaling in the liver resulting in diabetes." (PMID 40367133, 2025). "Disruption in insulin production or function can lead to the dysregulation of blood glucose, ultimately resulting in diabetes." (PMID 40801620, 2025). "Participant’s gender, diabetes duration, and method of insulin administration were significantly related to the FOH scores." (PMID 40357213, 2025). "The second and third most dominant markers were insulin and history of diabetes or high glucose levels.Uric Acid and other features were also identified as a potential clinical biomarker from our model." (PMID 40082942, 2025). "Insulin delivery has grown increasingly important in recent years due to the increasing global prevalence of diabetes mellitus." (PMID 39930590, 2025). "From a metabolic standpoint, the activation of PPARs is widely employed in the treatment of diabetes and dyslipidemia, owing to its efficacy in enhancing insulin sensitivity and modulating lipid distribution." (PMID 41216186, 2025). "Diabetes mellitus (DM) is a metabolic disease characterized by insulin resistance and defects in insulin secretion, which could cause long-term damage, dysfunction, or failure of various tissues and organs." (PMID 40070573, 2025). "Insulin-regulatedaminopeptidase (IRAP) is a zinc-dependent metalloenzymeidentified as a novel target for combating diabetes-induced diseasesdue to its crucial role in glucose metabolism and insulin sensitivityregulation." (PMID 40495656, 2025). "Diabetes is a chronic disease characterized by impaired insulin regulation and elevated blood sugar levels, leading to severe complications such as cardiovascular disease, renal failure, and neuropathy." (PMID 40017583, 2025). "For instance, several genetic variations in the calpain-10, the first gene identified in relation to diabetes, and adiponectin genes have been associated with T2DM by influencing insulin function and the amount of glucose produced by the liver." (PMID 40775340, 2025). "This glucose-dependent potentiation of insulin secretion is severely impaired in patients with type-2 diabetes mellitus." (PMID 40201698, 2025). "GCK, which encodes the β-cell glucose sensor glucokinase, was also downregulated in the diabetes cohort, as was the glucagon receptor which allows glucagon to positively influence insulin release within the paracrine environment of the islet." (PMID 40244011, 2025). "He told me that I was prediabetic and that if I kept going, the next step would be diabetes, and that I would have to take the medicines that are necessary, and possibly, after that, I would have to take insulin." (PMID 39945459, 2025). "It shows potential in managing diabetes via insulin signalling pathways and exhibits anti-inflammatory properties by activating nuclear factor erythroid 2-related factor 2 (Nrf2)." (PMID 40807390, 2025). "This suggests that herbal BJRD combined with insulin has a more pronounced efficacy in the treatment of diabetes." (PMID 40860518, 2025). "Insulin resistance (IR), defined as reduced sensitivity to the metabolic actions of insulin, is a key pathological feature of type 2 diabetes mellitus (T2DM)." (PMID 39920712, 2025). "Exogenous insulin can counteract the diminished response to insulin and effectively controlling blood glucose levels, thereby minimizing diabetes-related complications." (PMID 39815320, 2025). "In an animal model in which male Wistar rats were fed a high-fat diet for a period of three weeks and then treated with streptozotocin to induce diabetes, the administration of QE resulted in improved insulin sensitivity and reduced hepatic glucose production." (PMID 40807271, 2025).